BAP1 (BRCA1 associated deubiquitinase 1)
Diseases named in the same sentence as BAP1 in open-access papers (continued):
Sharing a sentence is not in itself a finding about the gene and the disease.
infection (10 papers, 2014 to 2023). The state of being infected such as from the introduction of a foreign agent such as serum, vaccine, antigenic substance or organism. "Other than the exopolysaccharide matrix production genes, another vps-coregulated protein, Bap1 (biofilm associated protein), also displayed a 2-fold increase in expression in infection of SS animals." (PMID 35573801, 2022). "Differences in the sequences of β-prismB and Cs lead us to hypothesize that RbmC and Bap1 will behave differently when interfacing with host surfaces that V. cholerae might encounter during infection." (PMID 37055389, 2023). "We depleted BAP1 in UM cells by lentiviral infection of cell with shRNA targeting BAP1." (PMID 25506912, 2014). "For example, this study indicates that hemocytes are a natural site of infection for SBV and that SBV results in higher bap1 expression in infected pupal cells." (PMID 34357313, 2021). "Transcriptome level analysis and in vivo experiments determined that bee antiviral protein-1 (bap1, GenBank: MF116383) plays an important role in honey bee antiviral defense, in the context of SINV-infection." (PMID 38468887, 2021). "The other infectious pools, AAP2, AAP3, BAP1, BAP2, BAP3, CAP1, and CAP2 might have carried the single infection of D. immitis, whose reactions putatively yielded 477-bp amplicons." (PMID 34027007, 2021).
adenocarcinoma (7 papers, 2016 to 2023). A common cancer characterized by the presence of malignant glandular cells. "For example, a report published by Pilarski and colleagues detected the development of an adenocarcinoma of unknown primary—which was defined as from CCA—in a patient with a BAP1 germline truncating mutation (c.1182C>G, p.Tyr394*)." (PMID 36013199, 2022). "We also report a positive correlation between BAP1 and patient outcome and provide evidence that BAP1 overexpression promotes migration and invasion of adenocarcinoma." (PMID 27553041, 2016).
neurodevelopmental disorder (5 papers, 2024 to 2026). A behavioral and cognitive disorder with onset during the developmental period that involves impaired or aberrant development of intellectual, motor, or social functions. "We were intrigued by the observation that some patients with germline BAP1 variants have been reported as being predisposed to tumors, whereas others have a neurodevelopmental disorder." (PMID 38969833, 2024).
genetic disease (3 papers, 2019 to 2025). "Another controversial issue in the characterization of BAP1-TPDS—and any other genetic disease—is the definition of the pathogenicity of a certain mutation." (PMID 35885614, 2022).
epithelial neoplasm (1 paper, 2022). A benign or malignant neoplasm that arises from and is composed of epithelial cells. "Meanwhile, the loss of BAP1 is not useful in cases in which the alternative diagnosis is another epithelial neoplasm." (PMID 35204459, 2022).
neurodegenerative disease (1 paper, 2024). A disorder of the central nervous system characterized by gradual and progressive loss of neural tissue and neurologic function. "Our ENS observations may be relevant to a broad range of human neurodevelopmental and neurodegenerative diseases because BAP1 impacts PRC activity." (PMID 38690732, 2024).
neuromuscular disease (1 paper, 2022). "Our data reveal the crucial role of Bap1-mediated SMN stabilization in Dpp4+ FAPs for the neuromuscular system and provide the possibility of cell-based therapeutics to treat neuromuscular diseases." (PMID 35603786, 2022).
BAP1 also shares sentences with these, for which no sentence is quoted: von Hippel-Lindau disease (6 papers); hereditary leiomyomatosis (5); blue nevus (4); cancer of the eye (4); ciliary body melanoma (4); Cowden syndrome (4); gastric adenocarcinoma (4); oculodermal melanocytosis (4); paraganglioma (4); sarcoma (4); tuberous sclerosis (4); glioblastoma (3); non-Hodgkin lymphoma (3); Papillary Meningioma (3); renal neoplasia (3); acinar cell carcinoma (2); acute myeloid leukemia (2); chronic myelomonocytic leukemia (2); colorectal (2); diabetes mellitus type 2 (2); Fanconi anemia (2); Gorlin syndrome (2); hereditary papillary renal cell carcinoma (2); hereditary tumor syndromes (2); neuroendocrine carcinoma (2); neurofibromatosis type 2 (2); nodular melanoma (2); non-small cell lung adenocarcinoma (2); ovarian serous cystadenocarcinoma (2); papillary thyroid cancer (2).
A further 100 diseases each share a sentence with BAP1 in 2 papers or fewer.